LYRM4 (LYR motif containing 4)
Description:
Stabilizing factor, of the core iron-sulfur cluster (ISC) assembly complex, that regulates, in association with NDUFAB1, the stability and the cysteine desulfurase activity of NFS1 and participates in the [2Fe-2S] clusters assembly on the scaffolding protein ISCU. The core iron-sulfur cluster (ISC) assembly complex is involved in the de novo synthesis of a [2Fe-2S] cluster, the first step of the mitochondrial iron-sulfur protein biogenesis. This process is initiated by the cysteine desulfurase complex (NFS1:LYRM4:NDUFAB1) that produces persulfide which is delivered on the scaffold protein ISCU in a FXN-dependent manner. Then this complex is stabilized by FDX2 which provides reducing equivalents to accomplish the [2Fe-2S] cluster assembly. Finally, the [2Fe-2S] cluster is transferred from ISCU to chaperone proteins, including HSCB, HSPA9 and GLRX5 (By similarity). May also participates in the iron-sulfur protein biogenesis in the cytoplasm through its interaction with the cytoplasmic form of NFS1.
Synonyms: C6orf149; ISD11; CGI-203; COXPD19
Tractability: Small molecule: a structure with a bound ligand is known. PROTAC: ubiquitination databases record sites on it; its protein half-life has been measured.
Gene: Protein-coding gene on chromosome 6 (5,102,595 to 5,260,950, reverse strand). Ensembl gene ENSG00000214113.
Subcellular location: Mitochondrion; Nucleus
Subcellular location (Human Protein Atlas): Nuclear bodies
Pathways (Reactome):
Metabolism: Complex III assembly; Maturation of TCA enzymes and regulation of TCA cycle; Mitochondrial iron-sulfur cluster biogenesis
Gene Ontology:
Molecular function: molecular adaptor activity; protein binding; protein homodimerization activity; structural molecule activity
Biological process: [2Fe-2S] cluster assembly; [4Fe-4S] cluster assembly; iron-sulfur cluster assembly
Cellular component: mitochondrial [2Fe-2S] assembly complex; mitochondrion; nuclear body; nucleus; iron-sulfur cluster assembly complex; L-cysteine desulfurase complex; mitochondrial matrix
Genetic constraint (gnomAD): Loss-of-function variants: 9 observed, 10.49 expected, observed/expected ratio (o/e) 0.86, 90% interval 0.52 to 1.49. The upper end of that interval is the gene's LOEUF score, 1.49, which puts it in group 6 of 6, group 1 being the genes least tolerant of losing a copy. Missense variants: 133 observed, 102.68 expected, observed/expected ratio (o/e) 1.3, 90% interval 1.12 to 1.5. Synonymous variants: 42 observed, 36.58 expected, observed/expected ratio (o/e) 1.15, 90% interval 0.9 to 1.49.
Homologues: Orthologues: guinea pig LYRM4 (92% identical), mouse Lyrm4 (89% identical), rabbit LYRM4 (88% identical), pig LYRM4 (86% identical), dog LYRM4 (77% identical), rat Lyrm4 (74% identical), zebrafish LYRM4 (53% identical), zebrafish lyrm4 (51% identical). Paralogues in human: SDHAF1 (29% identical).
Diseases named in the same sentence as LYRM4 in open-access papers:
LYRM4 is named in the same sentence as 35 diseases in open-access papers, as found by Europe PMC text mining. Sharing a sentence is not in itself a finding about the gene and the disease. The quoted sentences say what the papers report.
cognitive disorder (2 papers, 2023 to 2024). A disease affects cognitive processes. "Some others have been linked to cognitive disorders, for example LYRM4 has been linked to schizophrenia." (PMID 38488470, 2024). "Some others have been linked to cognitive disorders, for example LYRM4 with schizophrenia, and DDAH2* with multiple neurological conditions and psychiatric disorders." (PMID 36993650, 2023).
depression (2 papers, 2024 to 2025). "The seven positively selected depression-associated genes we identified in the human lineage are involved in brain development (PSEN2, ANKK1, PCDH9) and immunity (STAU1 and LYRM4), as highlighted in our results." (PMID 40075226, 2025).
Friedreich ataxia (2 papers, 2017 to 2021). An inherited condition that affects the nervous system and causes movement problems. "LYRM4 deficiency results in symptoms caused by frataxin deficiency associated with Friedreich’s ataxia, leading to the conclusion that LYRM4 facilitates FXN regulation of [2Fe-2S] cluster formation." (PMID 34573089, 2021).
CNS cancer (1 paper, 2021). "The mRNA level of LYRM4 was significantly decreased in kidney chromophobe (KICH), brain, and CNS cancer tissues compared with matched normal tissues." (PMID 34488769, 2021).
colon adenocarcinoma (1 paper, 2021). "LYRM4 mRNA was significantly overexpressed in colon adenocarcinoma (COAD), head and neck cancer (HNSC), kidney renal papillary cell carcinoma (KIRP), LIHC, lung squamous cell carcinoma (LUSC), and prostate adenocarcinoma (PRAD; p < 0.001)." (PMID 34488769, 2021).
colorectal cancer (1 paper, 2021). A primary or metastatic malignant neoplasm that affects the colon or rectum. "LYRM4 expression was higher in lymphoid neoplasms, such as diffuse large B-cell lymphoma (DLBC), leukaemia, sarcoma, thymoma (THYM), LIHC, colorectal cancer, gastric cancer, lung cancer, melanoma, and lymphoma, compared to normal samples." (PMID 34488769, 2021).
OXPHOS disease (1 paper, 2014). "Since then a mutation in LYRM4 has been identified in patients with combined OXPHOS disease." (PMID 24161539, 2014).
cancer (2 papers, 2021 to 2025). A tumor composed of atypical neoplastic, often pleomorphic cells that invade other tissues. "Overexpression of LYRM4[T] more strongly promotes the malignant phenotypes of NSCLC cancer cells compared to LYRM4[G]." (PMID 40285671, 2025). "Therefore, it is necessary to evaluate the expression of LYRM4 in pan-cancer and to investigate whether abnormal expression of LYRM4 is closely related to the tumorigenesis and development of LIHC." (PMID 34488769, 2021). "Finally, the expression of LYRM4 in pan-cancer was analysed using the TIMER2.0 database." (PMID 34488769, 2021).
mitochondrial disease (2 papers, 2020 to 2023). "A newly discovered gene for mitochondrial diseases, LYRM4, encodes ISD11 protein, which acts as an iron-sulfur cluster." (PMID 37810780, 2023).
tumor (2 papers, 2021 to 2025). "Then, we overexpressed LYRM4 with different rs9606 alleles and explore its effect on tumor phenotypes in vitro and in vivo." (PMID 40285671, 2025). "Pearson chi-square test analyses revealed that the mRNA expression of LYRM4 was significantly associated with tumour thrombus (p ˂ 0.05)." (PMID 34488769, 2021). "It is should also be noted that the mRNA expression of LYRM4 was significantly associated with tumour thrombus and encapsulation of HBV-related LIHC patients." (PMID 34488769, 2021). "Consistent with our in vitro findings, we found that LYRM4[T] overexpression facilitated tumor formation in vivo, compared with LYRM4[G] overexpression and control group." (PMID 40285671, 2025). "In particular, the expression level of LYRM4 was positively correlated with the degree of tumour progression and was undifferentiated in LIHC." (PMID 34488769, 2021). "Therefore, future studies should be warranted to investigate potential role of LYRM4 in metastasis, tumor microenvironment, and immune response." (PMID 40285671, 2025). "In addition, the mRNA expression of LYRM4 was significantly associated with ALT, tumour thrombus, and encapsulation of HBV-related LIHC patients." (PMID 34488769, 2021). "However, further subgroup analysis of the LYRM4 promoter methylation profile revealed great significance according to race, tumour grade, and nodal metastasis status in LIHC patients." (PMID 34488769, 2021). "However, there have been no reports on the differential expression of NFS1 and its auxiliary protein LYRM4 in tumour tissues." (PMID 34488769, 2021). "In addition, we analysed the association between LYRM4 mRNA expression and various clinicopathological factors of HBV-related LIHC using paired tumours and adjacent liver tissues from 157 patients." (PMID 34488769, 2021). "However, in LIHC normal tissues and LIHC tumour tissues, the co-expression correlation between LYRM4 and these genes was sequentially reduced, or even negatively correlated." (PMID 34488769, 2021). "Therefore, it is necessary to investigate whether the NFS1-interacting protein LYRM4 is differentially expressed in tumours and its role in carcinogenesis." (PMID 34488769, 2021). "Multivariate analysis showed that the mRNA expression of LYRM4 was related to ALT (glutamic-pyruvic transaminase), tumour thrombus, and encapsulation of HBV-related LIHC patients (p ˂ 0.05)." (PMID 34488769, 2021). "In addition, co-expression analysis was performed between LYRM4 and the genes involved in mitochondrial ISC biosynthesis in tumour and non-tumour tissues." (PMID 34488769, 2021).
LYRM4 also shares sentences with these, for which no sentence is quoted: hepatocellular carcinoma (2 papers); schizophrenia (2); alcohol abuse (1); alcoholic fatty liver disease (1); diffuse large B-cell lymphoma (1); gastric cancer (1); gastroesophageal reflux (1); head and neck cancer (1); infection (1); lactic acidosis (1); leukaemia (1); Leukoencephalopathy (1); lipid metabolism disorders (1); lung carcinoma (1); lung squamous cell carcinoma (1); lymphoid neoplasm (1); lymphoma (1); malaria (1); melanoma (1); neurological diseases (1); primary immunodeficiency (1); prostate adenocarcinoma (1); psychiatric disorder (1); sarcoma (1); thymoma (1).